Y_RNA (Y RNA )
Gene: Miscellaneous RNA gene on chromosome 6 (36,672,838 to 36,672,944, forward strand). Ensembl gene ENSG00000251864.
Homologues: Orthologues: chimpanzee Y_RNA (99% identical). Paralogues in human: Y_RNA (65% identical), Y_RNA (64% identical), RNY3 (64% identical), RNY3P1 (63% identical), Y_RNA (63% identical), RNY3P16 (62% identical), Y_RNA (62% identical), RNY3P2 (61% identical), RNY3P4 (61% identical), RNY3P7 (61% identical), RNY3P8 (61% identical), Y_RNA (61% identical), and 78 more.